MUC6 (mucin 6, oligomeric mucus/gel-forming (gene/pseudogene))
Diseases named in the same sentence as MUC6 in open-access papers (continued):
Sharing a sentence is not in itself a finding about the gene and the disease.
endocervical adenocarcinoma (3 papers, 2019 to 2021). An adenocarcinoma that arises from the endocervix. "It has been demonstrated that this morphologically defined variant of endocervical adenocarcinoma invariably shows a gastric immunophenotype: positive for HIK1083 (mouse monoclonal; KantoKagaku, Tokyo, Japan) and/or MUC6 expression (mouse monoclonal, CLH5; Novocastra Laboratories, Newcastle, UK)." (PMID 34680326, 2021). "All the Gastric-type endocervical adenocarcinoma cases were positive for MUC-6, and negative for p16." (PMID 34332600, 2021). "Immunohistochemically, MUC-6 and/or HIK1083 are usually negative and p16 is diffusely positive in intestinal-type endocervical adenocarcinoma." (PMID 31279344, 2019).
gastric ulcer (3 papers, 2018 to 2025). An ulcerated lesion in the mucosal surface of the stomach. "Previous studies highlighted the ability of ethanol to decrease the expression of TFF-2 as well as halting the gene expression of MUC-6 in gastric ulcer in rats." (PMID 40775122, 2025). "According to the results of qRT-PCR, the high-dose FPH treatment significantly increased the mRNA expression of MUC5AC and MUC6 in the gastric tissues of mice with ethanol-induced gastric ulcers." (PMID 36552666, 2022). "As the MUC2 mucin is important in intestinal protection and the MUC6 mucin protects the gastric glands genetic variation could play a role in related diseases such as inflammatory diseases and gastric ulcers." (PMID 30504806, 2018).
intraepithelial neoplasia (3 papers, 2023 to 2025). A precancerous neoplastic process that affects the squamous, glandular, or transitional cell epithelium without evidence of invasion. "Gastric-type low-grade intraepithelial neoplasia showed co-expression of carcinoembryonic antigen (CEA) and MUC6." (PMID 41404072, 2025).
invasive carcinoma (3 papers, 2016 to 2020). A carcinoma that is not confined to the epithelium, and has spread to the surrounding stroma. "Our cases expressed MUC6 strongly in high-grade dysplastic cells and invasive carcinoma cells." (PMID 27656307, 2016). "This is particularly evident for GIO and DIO mT models that showed an increase of invasive carcinoma compared to the lean mice models as well as a regulation of two pancreatic carcinoigenesis MUC5AC and MUC6." (PMID 32411709, 2020). "The pathological findings revealed invasive carcinoma derived from IPNB, and immunohistochemistry revealed positive expression of MUC1, MUC5AC, and MUC6, but negative expression of CDX2 and MUC2." (PMID 33097064, 2020).
lung adenocarcinoma (3 papers, 2013 to 2023). A carcinoma that arises from the lung and is characterized by the presence of malignant glandular epithelial cells. "To identify a possible association of MUC4, MUC6, and MUC12 with lung cancer, we analyzed the publicly available The Cancer Genome Atlas (TCGA) exome sequence data for lung adenocarcinoma and lung squamous cell carcinoma." (PMID 24947164, 2014). "Abnormal expressions of MUC1, MUC5 and MUC6 have also been related to the aggressive behavior of lung adenocarcinoma." (PMID 24176033, 2013).
lung carcinoma (3 papers, 2014 to 2024). "In ALK + lung cancer, there is a higher incidence of MUC1 and MUC5AC cytoplasmic expression, which, combined with a paucity of MUC2 and MUC6 expression, could lead to the biological aggressiveness of ALK + cancer." (PMID 36059804, 2022). "Analysis of 591 lung carcinoma tumor exomes from The Cancer Genome Atlas (TCGA) revealed that 20% of non-small-cell lung cancer tumors in smokers have mutations in at least one of the MUC4, MUC6 or MUC12 genes in contrast to only 6% in non-smokers." (PMID 24947164, 2014). "The frequency of positivity for MUC6 and preserved SMAD4 was low and, in comparison, not that different between primary lung cancers and pulmonary metastases from the GI tract." (PMID 37349623, 2024).
papillary adenocarcinoma (3 papers, 2023 to 2025). A morphologic variant of adenocarcinoma. "The immunostaining results showed that the foveolar-type papillary adenocarcinoma was positive for MUC5AC and had a high index of Ki-67, but the pyloric gland-type tubular adenocarcinoma was positive for MUC6 and had a low index of Ki-67." (PMID 38725617, 2024).
peptic ulcer disease (3 papers, 2021 to 2023). A digestive system disease characterized by discontinuation in the inner lining of the gastrointestinal (GI) tract because of gastric acid secretion or pepsin. "In the UK Biobank, ABO, CDX2, CCKBRMUC1, MUC6, FUT2, PSCA, and GAST genes have been identified and found to be associated with peptic ulcer disease." (PMID 36678166, 2023).
Alzheimer disease (2 papers, 2021 to 2024). A progressive, neurodegenerative disease characterized by loss of function and death of nerve cells in several areas of the brain leading to loss of cognitive function such as memory and language. "Notably, a previous WES study suggested that the variable number tandem repeat (VNTR) region of MUC6 is associated with late-onset Alzheimer’s disease, and a GWAS of Finnish twins found that a missense variant in MUC6 is associated with nicotine addiction." (PMID 38461185, 2024). "However, evidence of late-onset Alzheimer disease (LOAD)-associated genetic polymorphism within an exon of Mucin 6 (MUC6) and immediately downstream from the Adaptor Related Protein Complex 2 Subunit Alpha 2 (AP2A2) have been reported." (PMID 34976023, 2021).
celiac disease (2 papers, 2024 to 2025). An autoimmune genetic disorder with an unknown pattern of inheritance that primarily affects the digestive tract. "In untreated patients with coeliac disease, MUC6+ INFLARE metaplastic glands were distinguished from healthy MUC6+ Brunner’s gland cells by their mucosal localization." (PMID 39567783, 2024). "In the duodenum of patients with untreated coeliac disease, we observed more MUC6+ cells than in matched controls." (PMID 39567783, 2024).
chronic gastritis (2 papers, 2022 to 2024). Inflammation of the stomach that is chronic in nature. "As Helicobacter pylori can colonize deep within the glands where MUC6+ cells are located, we decided to test the hypothesis that AMPs found in inflamed mucosoids are upregulated in patients with H. pylori-related chronic gastritis." (PMID 39244776, 2024).
chronic pancreatitis (2 papers, 2005 to 2015). A chronic inflammatory process causing damage and fibrosis of the pancreatic parenchyma. "Our STP mice exhibited advanced ADM, increased fibrosis, increased numbers of PanIN lesions, overexpression of chronic pancreatitis-related marker Muc6, and elevated expression of desmoplasia-associated marker Col1A1, compared to the MT-TGFα mice." (PMID 25803032, 2015). "Therefore, we further assessed the expression of molecular markers that are associated with chronic pancreatitis (Muc6) or desmoplastic reaction (Ctgf1 and Col1A1)." (PMID 25803032, 2015). "This was confirmed by the upregulated expression of desmoplasia-associated Col1A1 and chronic pancreatitis-related Muc6 detected in the STP mice, indicating that STP mice may be a suitable animal model for studying the transition of chronic pancreatitis to pancreatic cancer." (PMID 25803032, 2015). "Given that mucin genes are highly conserved between human and mice and that MUC6 has been reported aberrantly expressed in human chronic pancreatitis, we sought to analyze Muc6 expression levels in the STP and MT-TGFα mice." (PMID 25803032, 2015). "The overexpression pattern of Muc6 suggests that our STP mice denote some molecular similarity with chronic pancreatitis, in addition to the fibrotic phenotype." (PMID 25803032, 2015). "While MUC1, MUC4, and MUC5AC are the most differentially overexpressed mucins in human PDAC, the selective increase of MUC6 expression was identified as a potential biomarker for human chronic pancreatitis when compared to normal pancreas and PDAC in an unbiased screen." (PMID 25803032, 2015).
ductal adenocarcinoma (2 papers, 2012 to 2019). "Both membrane-bound (MUC1, MUC3, MUC4) and secreted mucins (MUC2, MUC5AC, MUC5B, MUC6) are upregulated in ductal adenocarcinoma of the breast." (PMID 30682816, 2019). "MUC5AC expression in differentiating ductal adenocarcinomas from benign conditions demonstrated better operating characteristics than either MUC1 or MUC6." (PMID 23197977, 2012).
endometrial endometrioid carcinoma (2 papers, 2021 to 2023). "In addition, MUC-6 is positive in approximately 8% of benign epithelial cells, normal endometrial glands, and significant number of endometrial endometrioid carcinomas." (PMID 34332600, 2021).
gallbladder cancer (2 papers, 2021). "Immunohistochemistry for mucin type 6 (MUC6) using the anti-MUC6 antibody was performed on the sections representing the pancreatic duct and the gallbladder cancer." (PMID 34280877, 2021). "The presence of MUC6-positive pyloric gland metaplasia in the dilated pancreatic duct and gallbladder background mucosa in this patient suggests that IPMN and gallbladder cancer may have a common origin." (PMID 34280877, 2021). "Presence of mucin type 6 (MUC6) -positive pyloric gland metaplasia in both the dilated pancreatic duct and the gallbladder background mucosa suggests that pancreatic IPMN and gallbladder cancer may have a common phenotypic origin." (PMID 34280877, 2021). "The gallbladder cancer lesion was negative for MUC6, whereas the non-cancerous background mucosa was positive, consistent with pyloric gland metaplasia." (PMID 34280877, 2021). "We show that MUC6-positive pyloric gland metaplasia is present in the dilated pancreatic duct as well as in the gallbladder background mucosa, suggesting that IPMN and gallbladder cancer may have a common origin." (PMID 34280877, 2021).
gastroesophageal reflux disease (2 papers, 2017 to 2025). A chronic disorder characterized by reflux of the gastric and/or duodenal contents into the distal esophagus. "Ten gastroesophageal reflux diseases and five protein allergy studies in the literature were reported to link to MUC6." (PMID 28420126, 2017).
hyperplastic polyp (2 papers, 2010 to 2023). A polyp found mainly in the stomach and colon. "The fact is that the pattern of expression of MUC1, MUC2, and MUC6 that is reported in the present article for hyperplastic polyps, is identical to what is reported in other studies for normal mucosa." (PMID 20929551, 2010). "While the highest expression of MUC1, and MUC6 was observed in villous adenomas, they were totally absent in hyperplastic polyps." (PMID 20929551, 2010). "A total of 454 polyp specimens comprising 36 hyperplastic polyps, 15 serrated adenomas, 258 tubular adenomas, 114 tubulovillous adenomas, and 31 villous adenomas were included in this study, and were immunostained for MUC1, MUC2, MUC5AC and MUC6 by using mucin specific antibodies." (PMID 20929551, 2010). "In addition, meanwhile MUC6 was positive in about one third of tubulovillous adenoma and villous adenomas, it was negative in all hyperplastic polyps." (PMID 20929551, 2010).
hypertrophic cardiomyopathy (2 papers, 2023 to 2025). A condition in which the myocardium is hypertrophied without an obvious cause. "The MUC6 gene is expressed in the tissue of the stomach and pancreas, is linked to hypertrophic cardiomyopathy, and enhances innate immune reactivity and DM." (PMID 40572705, 2025). "The MUC6 gene located in 11p15.5 is expressed in the stomach and pancreas tissue, is associated with hypertrophic cardiomyopathy, and is involved in enhancing innate immune reactivity." (PMID 36979105, 2023).
intraductal papillary mucinous neoplasms (2 papers, 2021 to 2023). "In another study, analysis of EVs using a digital extracellular vesicle screening technique (DEST) reported the presence of a panel of mucins, including MUC1, MUC2, MUC4, MUC5AC, MUC6, and MUC13, in a cohort of 133 patients harboring intraductal papillary mucinous neoplasms (IPMN)." (PMID 36980526, 2023).
non-small cell lung carcinoma (2 papers, 2014 to 2023). A group of at least three distinct histological types of lung cancer, including non-small cell squamous cell carcinoma, adenocarcinoma, and large cell carcinoma. "On the other hand, the mutation status of MUC6 and three other genes (ATR, ERBB3 and KDR) was obtained as a marker for the recurrence of non-small-cell lung cancer (NSCLC) patients." (PMID 37504272, 2023). "We correlated the mutation frequency of MUC4, MUC6, and MUC12 with the non-small-cell lung carcinoma, and identified a distinct mutation frequency in tumor samples from smokers (20%) and non-smokers (6%), which cumulatively designates these MUC genes as diagnostic and prognostic markers in smokers." (PMID 24947164, 2014).
oral cancer (2 papers, 2023 to 2025). "Odds ratios (ORs) and 95% confidence intervals (CIs) of clinical statuses associated with genotypic frequencies of MUC6 rs6597947 in male oral cancer patients." (PMID 37581476, 2023). "Odds ratios (ORs) and 95% confidence intervals (CIs) of oral cancer associated with MUC6 genotypic frequencies." (PMID 37581476, 2023). "Odds ratios (ORs) and 95% confidence interval (CIs) of oral cancer associated with MUC6 genotypic frequencies among betel‐quid chewers." (PMID 37581476, 2023). "Odds ratios (ORs) and 95% confidence intervals (CIs) of oral cancer associated with MUC6 genotypic frequencies among non‐betel‐quid chewers." (PMID 37581476, 2023). "The mutations in MUC6 have been associated with malignancy and tumorigenesis of oral carcinoma." (PMID 40563552, 2025). "Moreover, male oral cancer patients who carried the AA + CC genotype at MUC6 rs6597947 had a lower risk of lymph node metastasis than other genotypes, suggesting a significant functional compromise and decompensated disease." (PMID 37581476, 2023).
ovarian tumor (2 papers, 2014 to 2021). "MUC6 encodes a protein associated with protecting epithelial surfaces against chemical agents and is related to ovarian tumours in mice." (PMID 34199109, 2021).
pneumonia (2 papers, 2018 to 2019). An acute, acute and chronic, or chronic inflammation focally or diffusely affecting the lung parenchyma, caused by an infection in one or both of the lungs (by bacteria, viruses, fungi, or mycoplasma.). "Furthermore, the association of MUC6 gene with pneumonia observed in our patients has recently been associated with RSV disease." (PMID 29751582, 2018). "No variants overlap between phenotypes, but there is some overlap at the gene level, namely, HLA-DRB1 in both OM and pneumonia and MUC6 in both bronchiolitis and pneumonia." (PMID 32010199, 2019). "Therefore, detection of MUC6 (mucin 6, oligomeric mucus/gel-forming) and MUC3A (mucin 3A, cell surface associated) as associated to pneumonia seems most relevant." (PMID 29751582, 2018).
polyp (2 papers, 2010 to 2017). A usually exophytic mass attached to the underlying tissue by a broad base or a thin stalk. "Considering the high clinical utility of the appropriate polyp classification, in this study, we evaluated the potential of colonic mucins (MUC1, MUC4, MUC17, MUC2, MUC5AC, and MUC6) and associated glycans (Tn/STn-MUC1 and CA19-9) for differentiating SSA/P from HP and TA." (PMID 27705923, 2017). "Regression analysis, with covariates of gender, age, polyp site, and MUC status included, indicated that negative staining for MUC2, Positive staining for MUC6, and left-sidedness would increase the risk of mucosal or muscularis mucosae invasion in colorectal polyps significantly." (PMID 20929551, 2010). "Nonetheless, no statistical significant could be found for difference of MUC6 expression level in various polyp types." (PMID 20929551, 2010).
thyroid cancer (2 papers, 2023). "Also, renal cell and thyroidal carcinomas showed MUC6 positivity in <1% of cases and are therefore considered unlikely sources for MUC6 positive metastases." (PMID 37057870, 2023).
tubular adenoma (2 papers, 2010 to 2023). A usually polypoid neoplasm arising from the glandular epithelium. "Here, we assessed GS‐II binding and performed immunostaining for HIK1083 (specific to terminal αGlcNAc residues), MUC5AC, MUC6, and special AT‐rich sequence binding protein 2 (SATB2) in SSLs, MVHPs, and tubular adenomas (TAs)." (PMID 37036163, 2023). "Immunohistochemical expression of MUC5AC, MUC6, and HIK1083 in tubular adenoma and sessile serrated lesion." (PMID 37036163, 2023).
villous adenoma (2 papers, 2010 to 2021). An epithelial neoplasm morphologically characterized by the presence of a villous architectural pattern. "Colonic villous adenoma-like growth pattern and immunohistochemical profile of MUC2-, MUC5AC- and CDX2-positivities but MUC1- and MUC6-negativities in the present case indicated that the lesion was consistent with the intestinal type IPMN." (PMID 34674710, 2021).
adenocarcinoma in situ (1 paper, 2017). A lesion in which the normally situated glands are partially or completely replaced by atypical cells with malignant characteristics. "Immunostaining for MUC5AC and MUC6 confirmed the diagnosis of adenocarcinoma in situ arising from Brunner's gland hyperplasia." (PMID 28512587, 2017).
ampullary adenocarcinoma (1 paper, 2011). "This study explored the relationships between diagnosis, identification, and survival of ampullary adenocarcinoma and the expressions of MUC1, MUC2, MUC5AC, and MUC6." (PMID 22027009, 2011). "Expression of MUC1 was high (72%) in ampullary adenocarcinoma, while expressions of MUC2, MUC5AC, and MUC6 were lower." (PMID 22027009, 2011). "For example, normal pancreatic tissue mainly expresses MUC1 and MUC6, while ampullary adenocarcinoma mainly expresses MUC1 and MUC5AC, along with MUC6 and MUC2." (PMID 22027009, 2011).
cervical adenocarcinoma (1 paper, 2021). An adenocarcinoma arising from the cervical epithelium. "According to the largest study focusing on this topic, gastric type cervical adenocarcinomas are positive for CK7 in 100% of cases, CK20 in 49%, CDX2 in 51%, Ca125 in 80%, PAX8 in 68%, ER in 6%, PR in 9% and MUC6 in 81% of cases." (PMID 33706757, 2021).
chronic obstructive airway disease (1 paper, 2018). "Furthermore, the association of the olfactory receptor gene OR9G9 has recently been related to some viral infectious diseases, while the role of mucin genes (MUC6 and MUC3A), encoding mucin glycoproteins, are well-known factors related to chronic obstructive airway disease." (PMID 29751582, 2018).